IL6 (interleukin 6)
Diseases named in the same sentence as IL6 in open-access papers (continued):
Sharing a sentence is not in itself a finding about the gene and the disease.
infection (continued). "The peak IL-6 levels at 14 days post-infection may be linked to its role in promoting antibody production, facilitating the differentiation of activated B cells into plasma cells, and possibly influencing macrophage polarization, favoring the alternatively activated M2 macrophage phenotype." (PMID 40918106, 2025). "IL‐6 inhibition may have different effects if used during post‐influenza bacterial pneumonia caused by different types of bacteria or if IL‐6 is inhibited at different time points during the course of infection." (PMID 39921246, 2025). "Together, the results suggested that B.1.351 β infection resulted in sustained activation of IL-6-encoded gene at least up to 4 weeks, which might promote retention of resident memory T cells in the absence of readily detectable cellular infiltrates within the brains." (PMID 39475775, 2024). "Compared to Prévotella bivia infection of three-dimensional human vaginal epithelial cells or GV infection of cervical epithelial cells, AV can induce a more intense pro-inflammatory immune response, causing vaginal epithelial cells to secrete a large amount of IL-6 and TNF-α." (PMID 39027438, 2024). "In contrast, Wild-type and IL-6−/− + rIL-6 brains had higher number of activated and phagocytic microglia in infected tissue, with these cell phenotypes surrounding the cryptococcomas or brain lesions, which are associated with stronger response to infection and tissue repair." (PMID 39334365, 2024). "IL-6 also recognizes whether fever in CART therapy is caused by infection or CRS." (PMID 39559703, 2024). "IL-6 levels increased at 2 dpi in both the S06-60% and oseltamivir groups (P < 0.05) but remained significantly lower than those in the positive control group (P < 0.01), suggesting that S06-60% could reduce inflammation and associated post-infection damage." (PMID 39883224, 2024). "The cytokine signalling pathways blocked by IL-6 inhibition, coupled with the inhibitory effect of steroids on neutrophil and macrophage function, may impair local and systemic immune responses to infection, potentially increasing the risk of secondary infection." (PMID 37978457, 2023). "Infection-associated induction of known inducers of myofibroblast differentiation (e.g. IL-6, IL-8, IL-11, EGF, and CTGF) may facilitate scarring in a paracrine fashion, by inducing myofibroblast differentiation or by sensitizing tissue-resident fibroblasts to pro-fibrotic stimuli." (PMID 37265500, 2023). "Moreover, the cytokine and chemokine patterns show a more evident mix of Th1 and Th2 response during the late phase of envenoming associated with the secondary infection inflammation, assigning some molecules, as IL-6 and IL-10, as possible novel markers for wound infection prediction." (PMID 37755950, 2023). "To explore potential reasons for the strong observational association and (largely) null genetic association, we performed further MR analyses to explore whether IL-6 signalling (which is known to alter the risk of infection) could alter particle count of small HDL leading to our observed results." (PMID 37814277, 2023). "The correct selection of patients who will benefit from treatment with IL-6 blockade and its timing decreases the probability of its low utility; however, inadequate immunosuppression can also impair virus clearance, increase the selection of variants of concern, and increase the risk of infections." (PMID 37147677, 2023). "If the anti-S antibody cannot neutralize the secondary infection due to the decay of antibodies and/or escape the mutation of newly emerged variants such as BA.2.86, the acquired anti-N antibody could be one of the causes of IL-6 induction." (PMID 37896795, 2023).
infection (continued). "Additionally, the analysis of SAPS-related inflammatory cytokines and chemokines in the supernatant of the infected lung slices revealed that infection with the omicron variant exclusively triggered an increased secretion of IL-1b, IL-6, IL-8, TNF-α, and IL-1β." (PMID 38095608, 2023). "Thus, combination alloferon/zanamivir might also be an effective treatment for inflammatory responses caused by infection with respiratory viruses, as well as for regulation of inflammatory responses in the lung mediated by IL-6 and MIP-1a." (PMID 36614125, 2022). "Thus, exacerbation of the patient’s condition may have been avoided by recognizing the dropped stones as a source of infection and IL-6 inhibitors as a risk factor for severe infection." (PMID 35389108, 2022). "The infection of C. perfringens can increase the expression of claudin-2 in intestine of broilers, which may be explained as a result of ‘cross-talk’ caused by IL-6 among JAK/STAT, SAP/MAPK and PI3K signaling pathways." (PMID 35436978, 2022). "Interestingly, a drop in plasma zinc levels is seen after infection, which could temporarily deprive the embryo of its zinc supply and cause a release of inflammatory cytokines such as IL-6." (PMID 35682762, 2022). "The early infection (3 dpc) triggered a strong transcriptional up-regulation of many immune genes in different organs including those encoding pro-inflammatory cytokines IL-1β, IL-6 and TNFα and other cytokines involved in the development of adaptive immunity (IL-8, IL-10, IL-22, IL-17C2, INFγ)." (PMID 34497310, 2021). "TCZ inhibits IL-6 in the immune response and changes the way how a patient’s immune system works, which may make patients more susceptible to infection or worsen the current infection, and even cause death due to deterioration of disease." (PMID 37287491, 2021). "The infection with SARS-CoV-2 might cause neurologic symptoms since cases with neuropsychiatric symptoms have been related to an increase of pro-inflammatory cytokine IL-6." (PMID 33917837, 2021). "Therefore, transient expression of CART-secreted aIL6 and IL1RA could minimize potential risk of increasing possibility of infection during CART treatment by impairing patients’ immunity through IL6 and IL1 sigaling blockade." (PMID 34518515, 2021). "Thus, patients with IL-6-174 GG polymorphism (C- carriers) may be susceptible to developing a severe infection due to SARS-CoV-2, leading to an increase in IL-6 levels that produce a cytokine storm related to impaired zinc homeostasis." (PMID 32754165, 2020). "Furthermore, in an intraperitoneal infection model, Dectin-1 knockout mice were less able to recruit neutrophils, monocytes, and eosinophils to the site of infection than wild-type mice and this was associated with a decrease in IL-6, CCL2, CCL3, G-CSF, and GM-CSF production." (PMID 32047726, 2019). "The higher levels of IL-6 verified may be associated with the role of this cytokine in the acute inflammatory response to infection through the activation and differentiation of T lymphocytes, stimulation of hepatic production of acute phase proteins, and antibody production by B lymphocytes." (PMID 31772504, 2019). "Infection and inflammation during pregnancy are hypothesized to be associated with induction of placental cytokines, including IL-6, and increased fetal exposure to pro-inflammatory cytokines can result in increased risk of infant neurologic injury, even in the absence of HIV." (PMID 30198049, 2018). "Several studies in subjects chronically infected with T. cruzi revealed that increased levels of IL-6 were associated with cardiac dysfunction, which supports the hypothesis that sustained inflammation in the chronic phase of infection may also alter the homeostatic mechanisms of T-cell maintenance." (PMID 30517089, 2018).
infection (continued). "Interestingly, however, IL-6 mRNA produced in MyD88-deficient macrophages was minimal after stimulation with poly I:C but was comparable to the level of control macrophages after infection with TMEV." (PMID 29410948, 2018). "Several studies have suggested that IL-6 is a pro-inflammatory cytokine in infection; however, other studies have shown that IL-6-deficient mice exhibit impaired resistance against S. pneumoniae, Listeria monocytogenes, and Escherichia coli, implying that IL-6 inhibits inflammation." (PMID 30116243, 2018). "Lower IL-1β secretion by PBMC was associated with peripheral infection at delivery and lower IL-6 secretion by PBMC was associated with placental infection during pregnancy, supporting the hypothesis that these pro-inflammatory cytokines may contribute to control maternal parasitaemia." (PMID 29743113, 2018). "In addition, the deficiency of IL-6, IL-23, or IL-17 receptor A (IL-17RA) impaired the compact granuloma formation and conferred susceptibility during infection, associated with reduced tumor necrosis factor-α, IFN-γ, and inducible nitric oxide synthase enzyme expression." (PMID 28871251, 2017). "Moreover, IL-6 deficient mice showed lower thymic depletion than wild type animals after infection." (PMID 28147332, 2017). "Also, severe disease after seasonal IV infections is associated with increased IL-6 levels." (PMID 28195157, 2017). "It is highly plausible that the diversion of the pro-inflammatory to anti-inflammatory response in carriers of the rs3750920 TT genotype may expose the individual to a higher risk as TNF and, IL-6 cytokines are important early in infection to keep the parasite in check." (PMID 28288644, 2017). "On the other hand, the strong activation of IL-6 in Ac2–26-stimulated LPLs suggests that this cytokine may play a key role in mucosal protection, since its absence was associated with marked infection-induced apoptosis in the colonic epithelium and subsequent ulcerations in a rat model." (PMID 27484833, 2016). "Cytokines utilizing the STAT3 signaling pathway including IL-6, IL-21, and IL-27 have been implicated in driving Tfh differentiation, but due to their partially compensatory pathways, separating the requirements for individual signals throughout infection has proved challenging." (PMID 25569154, 2015). "Furthermore, the EPs 7630 caused elevated IL-6 production during infection might strengthen the production of acute phase proteins, neutrophilic granulocyte generation in the bone marrow, and the establishment of adaptive Th17 and Th22 cells." (PMID 26406906, 2015). "However, the mechanism underlying the fine tuning of IL-6 expression especially in infection induced tolerance remains unclear." (PMID 25762865, 2015). "The increased IL-6 concentration in patients and household contacts when compared with controls may be due to release of IL-6 into circulation during early stages of infection causing systemic symptoms and hence the levels may also vary depending upon the clinical status of the patients or contacts." (PMID 26359865, 2015). "The increase in IL-1β, IL-6, and CXCLi2 transcription in the spleen and cecal tonsils shows that like S. Typhimurium and other broad-range serovars, S. Virchow elicits a strong immune response in the chicken, causing a rapid inflammatory response upon infection." (PMID 26664914, 2014). "Besides an extracellular or extrinsic role of enhancing antibodies, ADE may also enhance infection intrinsically by regulating the production of inflammatory-associated cytokines, such as IL-6, IL-10, IL-12, TNF-α and IFN-γ." (PMID 25329914, 2014). "One intraperitoneal injection of the complex immediately following infection with H. polygyrus resulted in a dramatic increase in the percentage of Foxp3+ Treg cells and increased expression of Helios on Foxp3+ T cells in the MLNCs of IL-6-deficient mice by day 7 postinfection." (PMID 24185641, 2014).
infection (continued). "Furthermore, since IL-6 stimulates immune responses when needed, e.g. during infection, susceptibility to microbes may be increased when Il6 is down-regulated." (PMID 24069384, 2013). "In this BA.5 cohort, vaccination remained protective; IL-6 was the most informative admission biomarker; bloodstream infections suggested gut translocation; and prior infection was an independent determinant of early post-acute symptom burden." (PMID 42197510, 2026). "Cerebrospinal fluid analysis showed elevated interleukin-6 and interleukin-8 levels in the infection-triggered encephalopathy syndromes group (area under the curve > 0.75 each)." (PMID 41929602, 2026). "In this context, IL‐6 assumes a predominantly proinflammatory profile, being released in response to infection or tissue injury." (PMID 41573125, 2026). "In contrast, at 24 h post-infection, there was a significant increase in IL-6 levels in p62-depleted macrophages, highlighting differences in the signalling pathways downstream of these cytokine receptors." (PMID 41583695, 2026). "This strategy is likely advantageous: IL-6 is often induced early in infection to recruit immune cells, but B. abortus can bypass this to activate STAT3 later, when dampening inflammation becomes critical for persistence." (PMID 41486271, 2026). "Specifically, the concentration of interleukin-6 (IL-6) in the serum of treated mice decreased to 9.98 ± 0.87 pg/mL at 30 h post-treatment, which was markedly lower than that in the infection control group (21.6 ± 0.64) pg/mL (p < 0.001)." (PMID 41596591, 2026). "Even with the similarity to the levels of the untreated control group (which only increased MIF after infection), stimulation with Strongyloides antigens appears to favor the secretion profile of IL‐4, IL‐6, and MIF in some conditions." (PMID 41399974, 2026). "In this study, we found that IL-6 was produced at high levels by both macrophages and fibroblasts following infection." (PMID 42003588, 2026). "Cytokines with the greatest contributions to PC1 included IL‐6, IL‐1β, and IFNγ, particularly among samples with secondary infection." (PMID 41488232, 2026). "Because IL-6 concentrations can vary greatly across different disease states, we investigated the concentration dependent effects of IL-6 on the neutrophil response to diverse bacterial pathogens using an infection-on-a-chip microfluidic device." (PMID 41822491, 2026). "We found Aph infection induced the expression of the hepcidin mRNA and protein, and strong IL-6, IL-1β, and TNF-α mRNA expression by host cells." (PMID 42294677, 2026). "This study aimed to describe the cytokine responses (IL-2, IL-6, IL-10, TNF-α, IFN-γ) associated with each infection." (PMID 41547724, 2026). "Analysis of inflammatory mediators revealed selective modulation of cytokine expression, with reduced interleukin-6 transcript levels at 20 days post-infection, whereas tumor necrosis factor alpha expression remained unchanged." (PMID 42081053, 2026). "Complementation with pBAH001 or pBAH002 partially rescued production of IL-8, IL-13, IFN-γ, IL-1β, and IL-6, with greater cytokine production occurring with ΔflgB (pBAH001) infection compared to ΔflgB (pBAH002)." (PMID 41459941, 2026). "Concurrently, infection triggered a pronounced pro-inflammatory response, with mRNA levels of IL-1β, IL-6, IL-8, and TNF-α significantly upregulated." (PMID 41584086, 2026). "In severe infection, mRNAs of IL‐4, IL‐5, IL‐6, IL‐10 and IL‐13 highly expressed compared to the non‐infected control, but the interferon‐ (INF)‐γ expression remained unaltered." (PMID 41503693, 2026). "In mouse models, high levels of IL-6, IL-5, IL-8, and granulocyte-macrophage colony-stimulating factor (GM-CSF) are predictive of ensuing infection." (PMID 41503525, 2026). "Collectively, these findings suggest that infection-induced IL-6 promotes plasmablast survival and antibody production." (PMID 42003588, 2026).
infection (continued). "We observed a significant decrease in the expression of IL-1β, TNFɑ and IL-6 in p62-depleted macrophages compared with WT macrophages only at 5 h post-infection." (PMID 41583695, 2026). "Independent predictors for infection were procalcitonin (≥0.40 ng/mL), IL-6 (≥84 pg./mL), and creatinine (≥1.35 mg/dL) (AUC 0.74)." (PMID 41647515, 2026). "Dynamic inflammatory marker patterns correlated with infection timing, and early peaks of CRP, WBC, and IL-6 were associated with worse outcomes." (PMID 41597404, 2026). "The ΔvipA1-hcp1 double mutant showed heightened IL-1β levels at 4 h (P < 0.0001) and 8 h (P < 0.01), with sustained IL-8 and IL-6 overexpression across all infection stages (P < 0.0001; P < 0.01)." (PMID 41347512, 2026). "Compared to the WT strain, the ΔvipA1 mutant significantly elevated IL-1β mRNA levels at 1 h (P < 0.05) and 4 h (P < 0.0001) post-infection and increased both IL-8 and IL-6 mRNA levels at 4 h (P < 0.001)." (PMID 41347512, 2026). "In p62-deficient macrophages, we observed reduced expression and secretion of key cytokines, such as IL-1β, TNFα and IL-6, early during infection." (PMID 41583695, 2026). "Post-infection depletion of neutrophils rescued mice from lethal infection by significantly reducing the bacterial burden and levels of IL-17A, IL-6, and TNF-α in peripheral blood." (PMID 42308351, 2026). "Infection disrupts pro-inflammatory cytokine balance (e.g., IL-6, IL-1β, IL-8, IL-10, IFN-γ, TNF-α), promoting leukocyte accumulation and inflammation." (PMID 41602759, 2026). "While IL‐1β, TNF‐α, and IL‐6 exhibited a declining trend following the initial peak within 72 h, implying potential resolution of the initial infection, the trajectory of HMGB1 levels remained inconspicuous and even continued to rise in the spleen until 72 h." (PMID 41551210, 2026). "Repetitive infection/stimulation with RV16 or poly(I:C) resulted in training of the IL‐6 release in human respiratory epithelial cells." (PMID 41099307, 2026). "Our results thus suggest that IL-6 is minimally expressed under homeostatic conditions but upregulated during infection or inflammation." (PMID 41397021, 2025). "During the acute phase of infection, a robust immune response is triggered, characterized by the release of pro-inflammatory cytokines such as interleukin-6 (IL-6), tumor necrosis factor-alpha (TNF-α), and interleukin-1β (IL-1β)." (PMID 41306980, 2025). "IL-6 levels were significantly elevated on day 9 post-infection in control dogs compared to vaccinees." (PMID 41159782, 2025). "Apoptotic markers (caspase-3, Bax, Bcl-2) were analyzed by immunofluorescence and immune genes expression kinetics (TLR3/7, RIGI, MDA5, IL-1β, IL-6, TNFα, IL-10, IFNβ and β-catenin) were measured at defined time points post-infection by RT-qPCR." (PMID 41157617, 2025). "At 48 h post-infection, IL-6 mRNA levels in the EV-A71 group were significantly higher than those in the RA- and RBV-treated groups (p < 0.05)." (PMID 40732670, 2025). "The widespread infection in RC cases plausibly necessitates an intense immune reaction, as reflected in the high salivary IL-6 levels observed in affected children." (PMID 40002706, 2025). "Infections significantly alter the levels of IL-6 and CRP in the body, proving that both biomarkers can indicate an inflammatory response due to infection, but they remain unaffected by smoking habits." (PMID 40242671, 2025). "Such factors include cytokines released during infection or inflammatory processes, such as interleukins-1 and 6 (IL-1 and IL-6), and tumor necrosis factor alpha (TNF-α) released in many inflammatory rheumatic diseases." (PMID 40723781, 2025). "IL-6 concentration was the same for all conditions at 24 h post-infection, but at 48 h, concentrations were higher in infected inserts." (PMID 40586572, 2025). "IL-1β is produced in conditions such as infection or tissue damage and triggers the production of various proinflammatory cytokines, including hypotension, fever, and IL-6." (PMID 40149596, 2025).